FOXP3 (forkhead box P3)
Diseases named in the same sentence as FOXP3 in open-access papers (continued):
Sharing a sentence is not in itself a finding about the gene and the disease.
tumor (continued). "Infiltration of TAMs CD68+/iNOS− and Tregs CD8+/FoxP3+ in the tumor stroma are negative prognostic factors with a positive correlation between them." (PMID 28343267, 2017). "Although our evidence is limited to depletion of peripherally derived Foxp3+ Treg cells, the increase in PFS indicates effective tumor control through the probable concurrent depletion of intratumoral Treg cells, thus removing the suppression of intratumoral effectors." (PMID 28880972, 2017). "Poor chemotherapy prognostic factors including lack of ER and PR expression, high tumor grade, and lymph node involvement, are associated with a significantly higher CD3+, CD8+ and FoxP3+ cellular infiltrate." (PMID 28085094, 2017). "Unfortunately, DCA is not tumor cell specific, therefore, the same shift in glucose metabolism occurs in immune cells, leading to induction of FOXP3+ Tregs." (PMID 28337200, 2017). "The proportion of CD4+CD25+FOXP3+ Treg cells was significantly higher in the different HCC tumor stage groups than in the control group; moreover, the proportion of CD4+CD25+FOXP3+ Treg cells was significantly higher in the advanced (stage III-IV) HCC group than in the early (stage I–II) HCC group." (PMID 28796055, 2017). "Alternatively, soluble signals derived from tumor B cells, (whose nature is still unknown), may allow the conversion of naive CD4+ T cells into Foxp3+ induced Tregs, similar to that reported for H. felis." (PMID 26657504, 2016). "In the absence of IL-10, impaired Treg-derived Nrp-1 suppressive functions and Foxp3 expression may be lost, allowing their transformation into effector CD4+ T cells to counteract tumor growth." (PMID 27075020, 2016). "Although there is a large amount of evidence that FoxP3+ T cells predominantly infiltrate tumor tissues, the detailed phenotypes of these FoxP3+ T cells have not been characterized." (PMID 27177223, 2016). "On the other hand, in the tumor compartment the number ranged from 0 to 21 (median: 1.8, mean: 3.5) for CD4, from 1 to 82 (median: 5.6) for CD8 and from 0 to 15 (median: 1, mean: 1.6) for FOXP3." (PMID 27463005, 2016). "Moreover, in the presence of the tumour, CD25+FoxP3+ Treg cells accumulate in the DLN of treated mice, reaching the same numbers as those found in untreated mice by day 14 after tumour inoculation." (PMID 27341421, 2016). "In this study, we could define tumor infiltrating Tregs in detail as CD45+CD4+CD25± and FOXP3+ cells and found that a higher frequency of Tregs among total examined cells was associated with a longer OS, and this result is in line with several prior reports." (PMID 26799288, 2016). "Up to now, Foxp3 expression has been found only in CD4+ T cells and in some tumor cell lines." (PMID 27350539, 2016). "A low number of Foxp3+ cells was observed out of the tumor cell area, while no FoxP3+ cells were detected in the tumor cell area." (PMID 27999289, 2016). "It was illustrated that miR-155 accelerated the accumulation of functional MDSCs in the tumor microenvironment by suppressor of cytokine signaling (SOCS) 1 repression and reduced ability to license the generation of CD4+Foxp3+ regulatory T cells (Tregs), thereby facilitating tumor growth." (PMID 27458169, 2016). "In particular, macrophages exposed to TGFβ1 have been shown to acquire an M2-like phenotype characterized by a number of tumor-promoting functions, including the ability to promote angiogenic activity, suppress T cell proliferation and induce CD4+ FOXP3+ Treg differentiation." (PMID 27589814, 2016). "In muscle-invasive bladder cancer, patients with FOXP3 expression in tumor cells had reduced long-term survival compared to patients with FOXP3-negative cancers." (PMID 27221038, 2016). "Furthermore, a significant reduction in the percentage of both CD25+FoxP3+ and CD25+CD127low regulatory T cell population was found both in the spleens and in the tumor lesions." (PMID 26911136, 2016).
tumor (continued). "The data above indicated that Tregs (FOXP3+) cells were the major players in the tumour immunosuppressive microenvironment, and, more importantly, ICOS+ FOXP3+ cells were the majority, which was characterized by superior survival and highly suppressive properties." (PMID 27725696, 2016). "Of interest, RdB/IL12/shVEGF treatment resulted in lowest accumulation of immunosuppressive regulatory T cells (Treg; FoxP3-positive), suggesting that RdB/IL12/shVEGF can reverse tumor-induced immunosuppression to enhance intratumoral infiltration of immune cells." (PMID 27821803, 2016). "FOXP3+ Tregs secreted TGF-β, which indicated that the suppression of anti-tumor immunity of FOXP3+ Tregs may be cytokine-dependent." (PMID 27566250, 2016). "Treg and TAM cells are key components of the tumor microenvironment, but Foxp3 is not expressed in normal oral mucosa." (PMID 28053372, 2016). "Despite the strong reduction in Foxp3+ T cells within the CD4+ T cell population at this stage of tumor growth, the CTL/Treg ratio in the B16SLC35A1 tumor was not different from that in B16scrambled tumors." (PMID 26741508, 2016). "However, no previous publications have evaluated prognostic performance of circulating tumor cells and CD4+CD25+Foxp3+Tregs." (PMID 27439521, 2016). "The observation describes that B cells may attenuate anti-tumor cytotoxic T cells responses and potentiate the local expansion of CD4+FoxP3+ Tregs in murine tumor environment." (PMID 27331871, 2016). "Our results indicate that depletion of FoxP3+ cells did not abrogate or apparently facilitate the anti-tumor effect of combination therapy as exhibited by bioluminescent imaging of the tumor." (PMID 27190629, 2016). "Overall, all studied T-cell phenotypes differed significantly between molecular subtypes, both in the invasive margin (CD3: p = 0.013; CD8: p < 0.001; FoxP3: p < 0.001 and CD3-ζ: p < 0.007) and the tumor center (CD3: p = 0.001; CD8: p = 0.042; FoxP3: p < 0.001 and CD3-ζ: p = 0.002)." (PMID 27473163, 2016). "In agreement with the immune profiling results, there was no noticeable expression change in the Foxp3 expression between treated and untreated tumours." (PMID 26883990, 2016). "Tr1 cells are not as well characterized as Foxp3+ Treg cells and have not received the same focus in tumor immunology research, but previous studies suggested that EBV, including other EBV+ tumors, induces Tr1 cells." (PMID 28033393, 2016). "Neither intravesical therapy (p = 0.694) nor Foxp3 expression was a significant predictor for tumor recurrence (p = 0.539)." (PMID 27557492, 2016). "T-VEC may support immunotherapy by enhanced by IFNγ and TNFα production, which can increase PD-L1 expression, promote influx of effector CD8+ T cell to the tumor microenvironment and decrease the number of CD4 + FoxP3+ regulatory T cells." (PMID 27660707, 2016). "Moreover, patients with high infiltration of FOXP3+ cells in the stroma and low infiltration of CD8+ in the tumor also presented inferior PFS (15.3 vs. 35.9 months, p = 0.035) and OS (17.4 vs. 68.8 months, p = 0.011)." (PMID 27463005, 2016). "Foxp3+RORγt+ T regulatory cells (Tregs) expand in CRC patients and may contribute to tumor development in part through the synthesis of IL-17A." (PMID 25839161, 2015). "Flow cytometry analysis of lung infiltrating OT-II cells showed that Foxp3+ T cells, but not IL-9+ Th9 cells, were induced in tumour-bearing mice in control Ig-treated mice." (PMID 26365427, 2015). "In 52/58 cases tumor sections could be stained for the presence of CD45+ cells, the presence of Tbet+ cells, as a measure for IFNγ-producing cells, and the presence of Foxp3+ cells for regulatory T cells." (PMID 26357849, 2015). "Furthermore, tumor infiltrating lymphocytes surrounding CD70+ tumor cells, showed a trend towards increasing FOXP3 expression and higher CD4/CD8 ratios." (PMID 25951351, 2015).
tumor (continued). "In contrast, we have shown before that a high number of FoxP3+ Tregs scored specifically within the tumour epithelium, especially relative to the number of CD8+ CTL, was correlated with poor survival, an observation also made in other tumour types." (PMID 25889974, 2015). "Given the ability of HIF-1α protein to degrade Foxp3 (refs 32, 33), we propose that DTX1 may also contribute to the stability of tumour-infiltrated Tregs by antagonizing HIF-1α." (PMID 25695215, 2015). "In addition, tumor cells can directly interfere with the immune system by releasing immunosuppressive factors or recruiting immunosuppressive cells, such as CD4+CD25+ Foxp3+ Tregs into the tumor microenvironment." (PMID 26551021, 2015). "We used a tumor microarray (TMA) including >600 clinically annotated CRC to address the prognostic significance of CRC infiltration by OX40+ cells, as evaluated in combination with CD8+ and FOXP3+ cell infiltration." (PMID 26439988, 2015). "Since a single FoxP3+ IL-17+ cell was only observed in two tumor samples (0.02 % of FoxP3+ cells), these cells were not further analyzed." (PMID 25795131, 2015). "While the majority of the tumor infiltrating immune cells did not express Tbet or Foxp3, an increased immune percentage of tumor occupied by CD45+ cells was associated with the enhanced tumor-infiltration by Tbet+ cells and Foxp3+ cells." (PMID 26357849, 2015). "We also observed that similar to human BCCs, the tumor stroma of murine BCCs show characteristic features of a Th2 microenvironment including increased expression of IL4 and the presence of cells expressing CD4/FOXP3." (PMID 26413810, 2015). "Importantly, the overlap between the three Treg subsets was comparable between HD-derived and OvCa patient-derived peripheral blood, CxCa-derived TDLN and tumor samples, indicating that CD25, CD127, and Foxp3 can also be used in cancer condition tissues." (PMID 26122357, 2015). "Next to the reduction in T cells, an expansion of Tregs could be found, marked by the high number of Foxp3+ cells and a strong correlation between PDL-1+ tumor cells and worse prognosis." (PMID 26605342, 2015). "In addition, tumor infiltrating mononuclear cells (TIMC) and T cell subpopulations (CD4, CD8, T-bet and FoxP-3) were quantified." (PMID 26496037, 2015). "The overall pooled analysis including all types of cancer suggested FoxP3+Tregs had a significant negative effect on overall survival (OS) (OR 1.46, P < 0.001), but the prognostic effect varied greatly according to tumor site." (PMID 26462617, 2015). "Foxp3+CD4+ T cells inhibit the activation of both CD4+ and CD8+ T cells, and within the tumor microenvironment may serve to suppress anti-cancer cell immunity." (PMID 26604855, 2015). "The emergence of FOXP3+CD3+CD56+ cells in tumor tissues, therefore, may impose an adverse effect on anti-tumor immunity." (PMID 26437631, 2015). "Even for HCC patients, the FOXP3-expressing CD3+CD56+ cells were only detected in tumor tissues but not in circulation." (PMID 26437631, 2015). "From this analysis, we were able to incorporate 2 out of 3 suppressive markers from our panel and identify a cluster of patients whose tumor demonstrated both low CD8+:FoxP3+ and low CD8+:PD-L1+ ratios; and we failed to generate TIL from these tumors." (PMID 26500776, 2015). "In addition, the relative numbers of CD4+CD25+Foxp3+ Tregs and CD8+ T cells were negatively correlated in the tissue of PDA patients, and the abundance of Tregs was significantly correlated with tumor differentiation." (PMID 24637664, 2014). "Furthermore, we confirmed that the expression of CD4 and CD8 as well as Foxp3, FR4, CD69, CD154, and CD25 was markedly decreased in the tumor tissues from the tumor-bearing BALB/c nude mice." (PMID 25365349, 2014). "The role of TNFR2/p75 in tumor biology was further substantiated by increased accumulation of CD4+ CD25+ FoxP3+ T regulatory cells (Tregs) that express TNFR2+ but not TNFR− Tregs in the LLC tumor model." (PMID 24664144, 2014).
tumor (continued). "In the present study, Foxp3-positive cell infiltration in the tumor tissue did not correlate with the patients’ survival or with other immunological parameters such as serum IL-8, IL-8(T) and CD163(IF)." (PMID 25461761, 2014). "However, during tumor formation and development the balance of CD4+IL-17+ Th17 and CD4+CD25+Foxp3+Treg can be disrupted by inflammatory cytokines." (PMID 24949077, 2014). "At 21 or 25 days after tumor implantation, splenic Tregs (CD4+CD25+FoxP3+) were analyzed." (PMID 24642245, 2014). "This thesis was further strengthened by Gobert's finding that only Treg cells located in these lymphoid aggregates actually expressed activation markers such as HCA-DR, GITR and ICOS, while FoxP3+Treg cells located within the tumor tissue itself did not." (PMID 25365237, 2014). "Moreover, Treg markers, such as forkhead box P3 (Foxp3) and folate receptor 4 (FR4), were more strongly expressed in the tumor tissues than the normal colon tissues and the cultured CT26 cells." (PMID 25365349, 2014). "In addition to tumor-specific T-lymphocytes, the TIL population is also comprised of immunosuppressive Foxp3+ regulatory T cells (Tregs) that play an important role in immune evasion." (PMID 25491880, 2014). "In these latter studies, the authors were unable to detect Foxp3 in naive or activated macrophages, but a detailed investigation in the tumor setting was not performed." (PMID 25264896, 2014). "They probably were able to elicit only a minimal CTL attack and subsequently attracted little to no Foxp3+ cells in their tumor micro-environment, possibly explaining their worse prognosis." (PMID 24997850, 2014). "Sections of this TMA were immunohistochemically stained and quantified for presence of Foxp3+ cells (Tregs) and tumor expression of HLA Class I and non-classical HLA-E and HLA-G." (PMID 24997850, 2014). "This Treg subpopulation was enriched in the peripheral blood of CRC patients, which correlated with tumor progression, suggesting that CD4+Foxp3+LAP+ Tregs may have clinical application as markers of tumor-specific Tregs in CRC patients." (PMID 25268580, 2014). "Tumor cells express CD25 and forkhead box P3 at the same time." (PMID 25289105, 2014). "Tumor-free lymph nodes were negative for cytokeratin, and had lower expression of Ki-67, Foxp3 and CD56 than other lymph nodes." (PMID 24885770, 2014). "Studies have shown a positive correlation between the number of tumour infiltrating effector T cells and patient survival, as well as a negative correlation with Foxp3+CD25HiCD4+ regulatory T cells." (PMID 24957270, 2014). "We detected similar levels of Foxp3 expression in M2 cells from WT and SCID mice suggesting an intrinsic expression of the protein in the macrophages rather than phagocytosis of Foxp3 from surrounding TRegs in the tumor microenvironment." (PMID 25264896, 2014). "Within this context, our results concerning FOXP3 protein expression are in accordance, since we observed a high expression in tumor cells of TNBC patients, who are exactly negative for HER2 expression by immunohistochemistry." (PMID 24877082, 2014). "Taken together, our observations of high proportions of CD4+CD25+FoxP3+ Tregs in tumors and CD8+ T cell recruitment blockage strongly support the possibility that these Tregs may inhibit local antitumor immunity at the tumor site." (PMID 24637664, 2014). "Depletion of these CD8+Foxp3+ Tregs in addition to CD4+Foxp3+ Tregs might allow for antitumor cytotoxic function of CD4+ T cells and tumor rejection." (PMID 22890822, 2013). "This experiment suggests that CD4+ T cells can mediate potent anti-tumor effects when cytotoxic CD8+ T cells are absent but that they are tightly controlled in their activity by Foxp3+ Tregs." (PMID 22890822, 2013). "High infiltration of FOXP3+ lymphocytes accompanied by a cytoplasmic FOXP3+ tumor was the most detrimental phenotype, although the FOXP3+ lymphocytes and the tumor were not significantly correlated in this study." (PMID 24649219, 2013).
tumor (continued). "Although FOXP3 expression in tumor cells was of no prognostic significance, FOXP3+ lymphocytes were significantly associated with poor overall survival (OS) (n=98, log-rank test P=0.008)." (PMID 24649219, 2013). "By contrast, nuclear FOXP3 expression in tumor cells appeared to attenuate the negative effect of FOXP3+ lymphocyte accumulation on OS." (PMID 24649219, 2013). "Unlike CD25 and CD127, which characterize Treg in both peripheral blood and tumor tissues, Tim-3 is not expressed by circulating Foxp3+ CD4 T cells, indicating that Tim-3 is specifically expressed on tumor associated Tregs." (PMID 23526963, 2013). "FOXP3 expression in tumor cells (cytoplasm and/or nucleus) showed no prognostic significance [hazard ratio (HR): 1.19; 95% confidence interval (CI): 0.45–3.13; P=0.722]." (PMID 24649219, 2013). "Elevated levels of Breg disturbed in tumor could transform CD4+ Treg into FoxP3+Treg via direct interaction with transforming growth factor-beta (TGF-beta) pathways, resulting in tumor proliferation." (PMID 23825635, 2013). "For FoxP3+ TIL density in the tumor center stromal compartment, we found a strong negative correlation with T4 stage (p = 0.01), node invasion (p<0.001) and VELIPI (vascular emboli, lymphatic invasion and perinervous invasion) criteria (p = 0.002)." (PMID 23613769, 2013). "By contrast, no significant positive correlation was observed between FOXP3 expression in tumor cells and high infiltration of FOXP3+ lymphocytes." (PMID 24649219, 2013). "In epithelial ovarian cancer the majority of Foxp3+ Treg cells accumulating in the tumor microenvironment expressed the ICOS, and tumor pDCs expressing the ICOSL were shown to be essential for the expansion and suppressive function of these regulatory Foxp3+ Tregs." (PMID 24282405, 2013). "As might be implied by the more promiscuous expression of CD25, relative to FoxP3 on or in Treg, respectively, CD25 mAb and FoxP3 vaccination have slightly different effects in tumor-bearing mice." (PMID 23720663, 2013). "The highest levels of FOXP3+ Tregs (3.5 ± 0.5%), > 15 fold increase compared with HFDs, were documented in patients whose tumours failed to undergo or had a poor pathological response (grades 1 and 2, respectively) to 8 cycles of NAC (spearmans Rho p = 0.004)." (PMID 23320561, 2013). "To test if this TGFβ production by tumor cells may be responsible for Treg accumulation in BLM-treated mice, we sorted CD4+ GFP+ from Foxp3-EGFP mice and stimulated them with T cell receptor (TCR) triggering." (PMID 23762310, 2013). "We also confirmed that MCF-7 cells expressed four FOXP3 isoforms lacking exon 3, 3-4, 3 and 8, and 3-4 and 8 (data not shown), supporting the idea that FOXP3 acts as a tumor suppressor." (PMID 24155921, 2013). "Similar to Foxp3 expression in BC, upregulation of CCL22 expression in tumor cells was significantly more common in carcinomas with unfavorable histological features, such as high tumor grade, ER-negativity, PR-negativity and HER2-overexpression." (PMID 24124553, 2013). "Paying particular attention to the micro-anatomic location in tumor tissues, here we observed that the majority of Tim-3+CD4+ cells in the peritumoral stroma were Foxp3−, whereas the majority of Tim-3+CD4+ cells in the cancer nest co-expressed Foxp3." (PMID 23526963, 2013). "Forkhead Box P3 (FOXP3) is a member of the forkhead/winged helix family of the transcription factors and plays an important role not only as a master gene in T-regulatory cells, but also as a tumor suppressor." (PMID 24155921, 2013). "Many reports, but not all, link these accumulations of CD4+FOXP3+CD25high Treg to poor prognosis presumably due to suppression of anti-tumor responses by the accumulating Treg." (PMID 23730621, 2013). "FOXP3 expression in TILs was significantly correlated with an absence of nuclear FOXP3 expression in tumor cells (P=0.002)." (PMID 24649219, 2013).